DCUN1D2 (defective in cullin neddylation 1 domain containing 2)
Description:
Contributes to the neddylation of all cullins by transferring NEDD8 from N-terminally acetylated NEDD8-conjugating E2s enzyme to different cullin C-terminal domain-RBX complexes and plays an essential role in the regulation of SCF (SKP1-CUL1-F-box protein)-type complexes activity.
Synonyms: DCNL2; C13orf17; FLJ10704; FLJ20092
Tractability: Antibody: the Human Protein Atlas places it where antibodies can reach. PROTAC: ubiquitination databases record sites on it; its protein half-life has been measured; a small molecule that binds it is known.
Gene: Protein-coding gene on chromosome 13 (113,455,819 to 113,490,984, reverse strand). Ensembl gene ENSG00000150401.
Subcellular location: Cytoplasm; Nucleus
Subcellular location (Human Protein Atlas): Cytosol; Plasma membrane
Pathways (Reactome):
Metabolism of proteins: Neddylation
Gene Ontology:
Molecular function: cullin family protein binding; protein binding; ubiquitin conjugating enzyme binding; ubiquitin-like protein binding
Biological process: positive regulation of protein neddylation; regulation of protein neddylation; protein neddylation
Cellular component: cytoplasm; nucleus; ubiquitin ligase complex
Genetic constraint (gnomAD): Loss-of-function variants: 22 observed, 23.14 expected, observed/expected ratio (o/e) 0.95, 90% interval 0.68 to 1.36. The upper end of that interval is the gene's LOEUF score, 1.36, which puts it in group 5 of 6, group 1 being the genes least tolerant of losing a copy. Missense variants: 254 observed, 258.71 expected, observed/expected ratio (o/e) 0.98, 90% interval 0.88 to 1.09. Synonymous variants: 99 observed, 96.27 expected, observed/expected ratio (o/e) 1.03, 90% interval 0.87 to 1.22.
Homologues: Orthologues: chimpanzee DCUN1D2 (99% identical), guinea pig DCUN1D2 (93% identical), mouse Dcun1d2 (91% identical), rat Dcun1d2 (90% identical), zebrafish dcun1d2a (85% identical), pig DCUN1D2 (84% identical), zebrafish dcun1d2b (64% identical), rabbit DCUN1D2 (64% identical), Drosophila melanogaster SCCRO (59% identical), dog DCUN1D2 (49% identical), Caenorhabditis elegans dcn-1 (41% identical), Drosophila melanogaster SCCRO4 (26% identical). Paralogues in human: DCUN1D1 (78% identical), DCUN1D3 (39% identical), DCUN1D4 (31% identical), DCUN1D5 (27% identical).
Diseases named in the same sentence as DCUN1D2 in open-access papers:
DCUN1D2 is named in the same sentence as 1 disease in open-access papers, as found by Europe PMC text mining. Sharing a sentence is not in itself a finding about the gene and the disease.
DCUN1D2 shares sentences with these, for which no sentence is quoted: tumor (1 paper).